H2AB2 (H2A.B variant histone 2)
Description:
Atypical histone H2A which can replace conventional H2A in some nucleosomes and is associated with active transcription and mRNA processing. Nucleosomes wrap and compact DNA into chromatin, limiting DNA accessibility to the cellular machineries which require DNA as a template. Histones thereby play a central role in transcription regulation, DNA repair, DNA replication and chromosomal stability. Nucleosomes containing this histone are less rigid and organize less DNA than canonical nucleosomes in vivo. They are enriched in actively transcribed genes and associate with the elongating form of RNA polymerase. They associate with spliceosome components and are required for mRNA splicing. May participate in spermatogenesis.
Synonyms: H2A.Bbd; H2AFB2; H2A.B.1
Gene: Protein-coding gene on chromosome X (155,380,709 to 155,381,299, forward strand). Ensembl gene ENSG00000277858.
Subcellular location: Nucleus; Chromosome
Gene Ontology:
Molecular function: protein binding; structural constituent of chromatin; DNA binding; protein heterodimerization activity
Biological process: mRNA processing; nucleosome assembly; heterochromatin formation
Cellular component: chromosome; euchromatin; nucleosome; nucleus
Homologues: Orthologues: chimpanzee H2AB3 (97% identical), macaque H2AB1 (88% identical), macaque H2AB2 (88% identical), mouse H2ab3 (57% identical), rat H2ab3 (57% identical), mouse H2ab1 (56% identical), mouse H2ab2 (50% identical), Drosophila melanogaster His2A:CG31618 (43% identical), Drosophila melanogaster His2A:CG33808 (43% identical), Drosophila melanogaster His2A:CG33814 (43% identical), Drosophila melanogaster His2A:CG33817 (43% identical), Drosophila melanogaster His2A:CG33820 (43% identical), and 15 more. Paralogues in human: H2AB3 (100% identical), H2AB1 (99% identical), H2AC21 (45% identical), H2AL1Q (45% identical), H2AX (45% identical), H2AC6 (44% identical), H2AJ (44% identical), H2AC11 (43% identical), H2AC12 (43% identical), H2AC13 (43% identical), H2AC14 (43% identical), H2AC15 (43% identical), and 15 more.